KCTD12 (potassium channel tetramerization domain containing 12)
Description:
Auxiliary subunit of GABA-B receptors that determine the pharmacology and kinetics of the receptor response. Increases agonist potency and markedly alter the G protein signaling of the receptors by accelerating onset and promoting desensitization (By similarity).
Synonyms: C13orf2; KIAA1778; PFET1; PFETIN
Tractability: Antibody: UniProt places it where antibodies can reach, with medium confidence; its Gene Ontology location is reachable by antibodies, with medium confidence. PROTAC: ubiquitination databases record sites on it; its protein half-life has been measured.
Gene: Protein-coding gene on chromosome 13 (76,880,175 to 76,886,405, reverse strand). Ensembl gene ENSG00000178695.
Subcellular location: Presynaptic cell membrane; Postsynaptic cell membrane
Subcellular location (Human Protein Atlas): Mitochondria
Gene Ontology:
Molecular function: identical protein binding; protein binding; RNA binding
Biological process: nervous system development; regulation of dendrite morphogenesis; regulation of G protein-coupled receptor signaling pathway; protein homooligomerization
Cellular component: postsynaptic membrane; presynaptic active zone membrane; receptor complex; presynaptic membrane
Genetic constraint (gnomAD): Loss-of-function variants: 16 observed, 16.06 expected, observed/expected ratio (o/e) 1, 90% interval 0.67 to 1.51. The synonymous counts are far from expectation, so gnomAD's model fits this gene poorly and the ratio says little. Missense variants: 452 observed, 412.62 expected, observed/expected ratio (o/e) 1.1, 90% interval 1.01 to 1.18. Synonymous variants: 260 observed, 184.15 expected, observed/expected ratio (o/e) 1.41, 90% interval 1.27 to 1.57.
Homologues: Orthologues: macaque KCTD12 (99% identical), mouse Kctd12 (99% identical), rat Kctd12 (99% identical), pig KCTD12 (98% identical), dog KCTD12 (98% identical), rabbit KCTD12 (98% identical), guinea pig KCTD12 (94% identical), tropical clawed frog kctd12 (76% identical), zebrafish kctd12.1 (62% identical), zebrafish kctd12.2 (60% identical), Drosophila melanogaster Ktl (35% identical), Caenorhabditis elegans F32B4.5 (22% identical). Paralogues in human: KCTD8 (56% identical), KCTD16 (52% identical), KCTD18 (23% identical), KCTD19 (23% identical), KCTD15 (21% identical), KCNRG (20% identical), KCTD1 (20% identical), KCTD14 (18% identical), KCTD21 (18% identical), KCTD6 (18% identical), KCTD7 (17% identical), KCTD11 (16% identical), and 1 more.
Diseases named in the same sentence as KCTD12 in open-access papers:
KCTD12 is named in the same sentence as 60 diseases in open-access papers, as found by Europe PMC text mining. Sharing a sentence is not in itself a finding about the gene and the disease. The quoted sentences say what the papers report.
bipolar disorder (6 papers, 2019 to 2025). A disorder of the brain that causes unusual shifts in mood, energy, activity levels and the ability to carry out day-to-day tasks. "Conversely, KCTD12 expression in the circulating CD11b+ macrophages of bipolar disorder patients is significantly higher as a percentage than that in healthy controls." (PMID 37238588, 2023). "KCTD12, significant at gene level in the present study, emerged as a candidate in a bipolar depression GWAS among Han Chinese44." (PMID 30886212, 2019). "Varying levels of evidence support their roles in neurocognitive disorders (KCTD3), neurodevelopmental disease (KCTD7), bipolar disorder (KCTD12), autism and schizophrenia (KCTD13), movement disorders (KCTD17), cancer (KCTD11), and obesity (KCTD15)." (PMID 31197948, 2019).
colon cancer (6 papers, 2017 to 2025). "Abnormal KCTD12 expression is closely linked to tumor development, and we confirmed its downregulation in primary colon cancer tissues." (PMID 40221412, 2025). "TCGA data revealed a significant downregulation of KCTD12 at both mRNA and protein levels in colon cancer compared to normal tissues." (PMID 40221412, 2025). "In colon cancer, KCTD12/CDK1 fusion positive tumors have been shown to become vulnerable to vemurafenib via a coadjuvant treatment with adefovir dipivoxil." (PMID 33520715, 2020). "There is a controversy in KCTD12 function in which, KCTD12 plays as an oncogene in gastrointestinal stromal tumors; and as a tumor suppressor in colon cancer." (PMID 30157793, 2018). "Based on this, we hypothesize that MSL1 induces ferroptosis via SLC7A11 suppression, potentially inhibiting colon cancer progression through its interacting with KCTD12." (PMID 40221412, 2025). "Elucidating KCTD12’s role in colon cancer could provide new insights for targeted therapies and improve patient outcomes." (PMID 40221412, 2025). "Moreover, disruption of the interaction between CDK1 and KCTD12 using Adefovir dipivoxil has been shown to reduce in vivo tumorigenesis of colon cancer cells and induce vemurafenib sensitivity in xenografts." (PMID 36266723, 2022). "Adefovir dipivoxil that interrupts the interaction between CDK1 and KCTD12 and induces cell cycle arrest at G2 could inhibit colon cancer cells proliferation and induce sensitivity to vemurafenib." (PMID 36266723, 2022). "In this study, we found that Erastin-induced ferroptosis in colon cancer cells significantly reduced MSL1 expression, suppressing the H4K16ac enzyme activity of the MOF/MSL complex and upregulating KCTD12 expression." (PMID 40221412, 2025). "TIMER analysis confirmed a negative correlation between MSL1 and KCTD12 in colon cancer cells (cor = −0.339)." (PMID 40221412, 2025). "Furthermore, we found that MSL1 downregulation, via modulation of KCTD12, suppresses the expression of key negative regulators of ferroptosis, SLC7A11 and GPX4, thereby promoting Erastin-induced ferroptosis in colon cancer cells." (PMID 40221412, 2025). "Notably, in colon cancer cells, the ferroptosis inducer Erastin significantly suppressed MSL1 expression, leading to KCTD12 upregulation." (PMID 40221412, 2025). "In fact, KCTD12 interacts with CDK1 and CDC25B, forming a complex that supports CDK1 phosphorylation and cell cycle progression, while pharmacological inhibition of KCTD12-CDK1 interaction suppresses growth of colon cancer cells in vitro and in vivo." (PMID 34001146, 2021).
colorectal cancer (6 papers, 2016 to 2025). A primary or metastatic malignant neoplasm that affects the colon or rectum. "It is worth noting that similar effects are induced on colorectal cancer cells by the misregulation of KCTD12, a protein that is distantly related to KCTD1." (PMID 36979172, 2023). "It is worth noting that similar effects on colorectal cancer cells are induced by the misregulation of KCTD12, a protein that is distantly related to KCTD1." (PMID 36979172, 2023). "Colorectal cancer stem cells have also shown a down regulation of KCTD12 which is a differentiation factor in relation with ERK pathway." (PMID 30157793, 2018). "KCTD12 over expression in colorectal cancer repressed stemness through down regulation of CD44, CD133, and CD29." (PMID 30157793, 2018). "Notably, reduced KCTD12 expression enhances the stemness of colorectal cancer cells—promoting self-renewal, tumorigenesis, and drug resistance—through modulation of the ERK pathway downstream of GABA signaling, leading to poor prognosis." (PMID 40221412, 2025). "Indeed, it has been reported that KCTD12 downregulation or overexpression dramatically increases and represses colorectal cancer cell stemness." (PMID 36979172, 2023). "Moreover, the similarities in the effects of KCTD1 and KCTD12 on colorectal cancer cell lines suggests novel, previously unreported similarities in the activities of members of the KCTD protein family." (PMID 36979172, 2023). "KCTD12 has been reported to be a prognostic biomarker of colorectal cancer and breast cancer." (PMID 36534449, 2022). "The similar effects produced on colorectal cancer cell lines by KCTD1 and KCTD12 suggest novel, previously unreported analogous activities among members of the KCTD protein family." (PMID 36979172, 2023). "Interestingly, the evaluation of the expression levels of KCTD12 and KCTD15—which are related to KCTD1—in colorectal cancer using TCGA data highlights similar downregulation." (PMID 36979172, 2023).
breast carcinoma (4 papers, 2022 to 2026). "Several studies have indicated that elevated expression of potassium channel tetramerization domain containing 12 (KCTD12) is linked to a positive prognosis in various tumors, including esophageal carcinoma and breast cancer." (PMID 38430429, 2024). "References: René Aquarius, Comments on "KCTD12 promotes G1/S transition of breast cancer cell through activating the AKT/FOXO1 signaling," PubPeer, August 2024." (PMID 41944200, 2026). "Previous studies have primarily focused on the role of KCTD genes in neurodevelopmental disorders and a few cancer types, such as KCTD12 in gastrointestinal and breast cancers, where it was reported to influence tumor progression and cell signaling pathways." (PMID 40832836, 2025). "Our expression analysis findings are consistent with the existing literature, where KCTD12 has been previously reported to be upregulated in various cancers, including gastric and breast cancers, contributing to tumorigenesis by promoting cell survival and proliferation." (PMID 40832836, 2025).
gastrointestinal stromal tumor (4 papers, 2016 to 2023). "It has been shown that the expression of potassium channel tetramerization domain containing 12 (KCTD12) as a regulator of GABAB receptor signaling is reversely associated with gastrointestinal stromal tumors." (PMID 30157793, 2018). "Moreover, KCTD12 can be a prognostic factor of gastrointestinal stromal tumors (GISTs)." (PMID 30157793, 2018). "KCTD12 has been widely studied in gastrointestinal stromal tumors (GIST)." (PMID 37626178, 2023).
lung carcinoma (4 papers, 2017 to 2024). "Moreover, we confirmed the cancer-promoting effects of KCTD12 in lung cancer A549 cells by performing gain- and loss-of-function experiments." (PMID 28869606, 2017). "An example includes KCTD12, which is a mitotic target but upon overexpression in cervical and lung cancers promotes tumorigenesis in an AURKA-dependent manner." (PMID 39334449, 2024). "The immunohistochemical analysis of KCTD12 expression in 75 pairs of lung cancer tissues and corresponding normal tissues showed the similar results." (PMID 28869606, 2017). "More importantly, higher KCTD12 expression in primary tumors is significantly correlated with unfavorable tumor stages and shorter survival in patients with lung cancer." (PMID 28869606, 2017). "We noted the existence of a significant correlation between tumor KCTD12 expression levels and tumor size, as well as pathologic T stage, in the 88 lung cancer patients who underwent pre-therapy surgery." (PMID 28869606, 2017). "The results of this analysis showed that majority of lung cancer tissues showed moderate-to-high KCTD12 expression, whereas all the normal tissues showed undetectable KCTD12 expression." (PMID 28869606, 2017). "In other contexts, KCTD12 may promote cell proliferation: increased expression of KCTD12 has been observed in cervical, colon and lung cancers and its high levels have been correlated with poor prognosis." (PMID 34001146, 2021). "Furthermore, we performed in vitro and in vivo experiments to determine the function of KCTD12 in cell cycle regulation and tumorigenesis, as well as its clinical significance in cervical cancer and lung cancer." (PMID 28869606, 2017). "In this study, we found that KCTD12 plays an important role in cell cycle regulation and tumorigenesis in cervical and lung cancers and report for the first time that KCTD12 is frequently upregulated in cervical and lung cancers." (PMID 28869606, 2017). "The data showed that KCTD12 expression was significantly upregulated in cervical and lung cancers." (PMID 28869606, 2017). "Furthermore, to determine whether KCTD12 can be a prognostic marker for patients with cancer, we performed an immunohistochemical analysis of KCTD12 expression in a cohort of patients with lung cancer with survival data." (PMID 28869606, 2017).
bipolar I disorder (3 papers, 2013 to 2023). A bipolar disorder that is characterized by at least one manic or mixed episode. "A genome-wide association study found that a polymorphism in the promoter region of the KCTD12 gene is associated with bipolar I disorder." (PMID 23843457, 2013).
Obesity (3 papers, 2016 to 2025). Accumulation of substantial excess body fat. "Additionally, we identified several genes with cASE that have been associated with diabetes (GIPC1, USP36, RNF213, KCTD12) or obesity (PIP5K1A) (78, 79, 81, –, 83)." (PMID 27709125, 2016). "Obesity also consistently altered 5 proteins in DMBA-exposed mice, including HNRNPC, HNRNPD, HSPA9, RPL36A, and KCTD12." (PMID 39910959, 2025).
uveal melanoma (3 papers, 2018 to 2023). A melanoma derived from melanocytes of the uveal tract. "KCTD16 has been found to be associated with thyroid cancer, while KCTD12, a member of the KCTD family, has been found to be associated with uveal melanoma." (PMID 31146393, 2019). "In addition, high levels of KCTD12 were positively correlated with disease-free survival (DFS) in LIHC (P = 0.032) and SARC (P = 0.026) patients but negatively with LGG (P = 0.004), THCA (P = 0.034), and uveal melanoma (UVM, P = 0.041)." (PMID 37626178, 2023).
depression (2 papers, 2013 to 2023). "Likewise, KCTD12 has been associated with depressive disorders and schizophrenia." (PMID 23843457, 2013).
esophageal squamous cell carcinoma (2 papers, 2018 to 2021). Esophageal squamous cell carcinoma (ESCC) is a type of esophageal carcinoma (EC) that can affect any part of the esophagus, but is usually located in the upper or middle third. "Moreover, role of KCTD12 in 5FU resistance introduces that as an efficient marker for the epigenetic targeted therapy of esophageal squamous cell carcinoma." (PMID 30157793, 2018). "In present study we examined the probable role of KCTD12 in regulation of several signaling pathways and chromatin remodelers in esophageal squamous cell carcinoma (ESCC)." (PMID 30157793, 2018). "Moreover, KCTD12 acts as a tumor suppressor also in esophageal squamous cell carcinoma (ESCC), downregulating WNT and NOTCH signaling." (PMID 34001146, 2021). "In this study, we assessed the role of KCTD12 on expression patterns of different pathways and cellular processes such as NOTCH/WNT signaling pathways, chromatin remodelers, and HOX genes in esophageal squamous cell carcinoma." (PMID 30157793, 2018).
medulloblastoma (2 papers, 2018 to 2019). A malignant, invasive embryonal neoplasm arising from the cerebellum. "Among the 25 human KCTD family members, several have been linked to human cancers, including KCTD8, KCTD12, TNFAIP1 and most notably KCTD11/Ren/KCASH1, a reported tumor suppressor in medulloblastoma, possibly by suppressing Hedgehog signaling." (PMID 30142151, 2018).
thyroid cancer (2 papers, 2019 to 2023). "KCTD12 levels increased with tumor progression in BLCA, BRCA, SKCM, STAD, and thyroid carcinoma (THCA)." (PMID 37626178, 2023).
Tinnitus (2 papers, 2023). Tinnitus is an auditory perception that can be described as the experience of sound, in the ear or in the head, in the absence of external acoustic stimulation. "KCTD12 may thus represent a potential target in the therapy of hearing disorders, and it is therefore essential to understand both the mechanisms of its effects in the auditory system and its role in animal models of tinnitus." (PMID 37635966, 2023). "Therefore, changes in KCTD12 action could contribute to sensorineural hearing loss due to impaired cochlear K+ homeostasis and impaired GABAB function in the auditory pathway, leading to tinnitus." (PMID 37635966, 2023).
acute lymphoblastic leukemia (1 paper, 2023). Leukemia with an acute onset, characterized by the presence of lymphoblasts in the bone marrow and the peripheral blood. "Thus, among all the KCTDs examined, only two pairs of them seem to be able to discriminate not only between the ALL subtype and the relative healthy counterpart, but also between the two types of acute lymphoblastic leukemia: KCTD12 and KCTD3 for B-ALL, and KCTD1 and KCTD11 for T-ALL." (PMID 37297863, 2023).
Anxiety (1 paper, 2014). Intense feelings of nervousness, tension, or panic often arise in response to interpersonal stresses. "Loss of Kctd12 results in increased branching/elaboration and decreased anxiety." (PMID 25329151, 2014).
cervical cancer (1 paper, 2017). A primary or metastatic malignant neoplasm involving the cervix. "Analysis of the gene expression profiles of two cohorts of patients from the Gene Expression Omnibus (GEO) database also showed that KCTD12 expression is markedly upregulated in cervical cancer tissue compared with normal tissue." (PMID 28869606, 2017). "To determine the clinical significance of KCTD12 in cervical cancer, we searched for a tissue microarray with survival data." (PMID 28869606, 2017). "To determine the clinical significance of KCTD12 in human cancer, we examined KCTD12 expression levels by immunohistochemistry using a tissue microarray containing 93 pairs of primary cervical cancer tissues and adjacent normal tissues." (PMID 28869606, 2017).
cervical squamous cell carcinoma (1 paper, 2023). A squamous cell carcinoma arising from the cervical epithelium. "The expression of KCTD12 was positively correlated with the degree of cancer-associated fibroblasts infiltration in cervical squamous cell carcinoma and endocervical adenocarcinoma (CESC), head and neck squamous cell carcinoma (HNSC), PAAD, and stomach adenocarcinoma (STAD)." (PMID 37626178, 2023).
developmental delay (1 paper, 2025). "Other candidate AD genes include DACH1, KCTD12, KLF5, and RBM26, all of which have been implicated in syndromic developmental delay, neuropsychiatric traits, or cancer predisposition based on case reports or CNV analyses." (PMID 40978814, 2025).
laminopathies (1 paper, 2012). "We examined the effect of mutant TMEM43 on mRNA expression of four genes, LMO7, KCTD12, MBNL2 and RAP2A, located on chromosome 13, that have been shown to have abnormal expression in the setting of laminopathies with striated muscle dysfunction." (PMID 22458570, 2012).
melanoma (1 paper, 2017). A malignant, usually aggressive tumor composed of atypical, neoplastic melanocytes. "Previously, it has been shown in B16 murine melanoma cells that KCTD12 is up-regulated in hypoxic conditions, and thus it may play a role in the hypoxic responses." (PMID 28448578, 2017).
neuroblastoma (1 paper, 2019). Neuroblastoma (NB) is the most common solid, extracranial childhood tumor. "In human SH-SY5Y neuroblastoma cells, lithium treatment increased the percentage of KCTD12 expression." (PMID 31311980, 2019). "Our present study also demonstrated for the first time the relationships among lithium, GADL1, and KCTD12 in human neuroblastoma cells." (PMID 31311980, 2019). "In this study, we addressed how lithium and GADL1 influenced the activity of GSK-3, which regulated the expression of KCTD12 using the GADL1 stable overexpression neuroblastoma cell line." (PMID 31311980, 2019). "Furthermore, we addressed for the first time the effects of lithium and GADL1 on the regulation of KCTD12 expression in human neuroblastoma cells." (PMID 31311980, 2019). "We hypothesized that lithium or GADL1 could regulate KCTD12 expression, and herein investigated the mechanism underlying the regulation of KCTD12 expression by lithium and GADL1 in the human neuroblastoma cells, SH-SY5Y." (PMID 31311980, 2019).